CRP (C-reactive protein)
Diseases named in the same sentence as CRP in open-access papers (continued):
Sharing a sentence is not in itself a finding about the gene and the disease.
periodontitis (continued). "Its administration has also been associated with reduced levels of other biomarkers of periodontitis, including CRP, ALP, and PCT." (PMID 39912085, 2024). "The association of periodontitis status and CRP levels with mortality was assessed using a survey-weighted Cox model." (PMID 39453923, 2024). "The findings of this study suggest that participants with periodontitis had elevated CRP levels and that periodontitis with CRP levels of > 0.5 mg/dL was a risk factor for mortality." (PMID 39453923, 2024). "The conducted studies also revealed an association between chronic periodontitis and elevated levels of plasma C-reactive protein (CRP)." (PMID 38473858, 2024). "Prior studies among PLWH have found an association between increased severity of periodontitis and increased prevalence of P. gingivalis, elevated C-reactive protein (CRP) levels, and higher proportions of circulating CD8 + cells." (PMID 38826270, 2024). "This study showed that approximately 13% of adults had periodontitis, with an analysis of all participants revealing a positive association between CRP level and periodontitis severity." (PMID 39453923, 2024). "This pinpoints periodontitis as a modifiable risk indicator for systemic comorbidity, as previous studies have suggested that hs-CRP levels of greater than 2.03 considerably increase the risk for CVD and can be reversed following treatment." (PMID 39101637, 2024). "In PerioGene North, high hs-CRP levels were associated with periodontitis after adjustment for potential confounders." (PMID 39101637, 2024). "Elevated levels of TNF‐α, IL‐6, and CRP in the plasma of periodontitis patients are closely associated with obesity." (PMID 39675010, 2024). "Inflammatory lesions, such as those caused by periodontitis, can also contribute to an increase in systemic inflammation and elevated CRP levels." (PMID 39062000, 2024). "Although the association of periodontitis with pregnancy complications is weaker compared to other factors, such as paternity, gestational age, and medical history, elevated levels of CRP and fetal tyrosine kinase increase preeclampsia risk." (PMID 38672972, 2024). "CRP is generally associated with higher levels in smokers, and severe periodontitis is associated with increased CRP serum levels compared with otherwise healthy patients." (PMID 38627806, 2024). "Measuring CRP levels can help identify high-risk individuals, and effective treatment of periodontitis can reduce CRP levels and systemic complications." (PMID 39453923, 2024). "Individuals with periodontitis exhibited higher levels of serum inflammatory markers, such as C-reactive protein (CRP) and interleukin-6 (IL-6), which are associated with an increased risk of cognitive impairment and AD." (PMID 39768299, 2024). "Comparing groups with or without periodontitis, they found an association between atherosclerosis and periodontitis to be associated with inflammatory CRP and IL-6." (PMID 38774039, 2024). "Only a few studies have examined the association between CRP levels in pregnant women and periodontitis." (PMID 37511934, 2023). "This study sought to investigate the association between BMI and periodontitis and between CRP and periodontitis." (PMID 37481511, 2023). "Genetically proxied downregulation of IL-6 signaling was associated with lower odds of periodontitis (odds ratio (OR) = 0.81 per 1-unit decrement in log-CRP levels; 95% confidence interval (CI): [0.66;0.99]; P = 0.0497)." (PMID 37342352, 2023). "This study is the first study to analyze the effects of IL-6 -572 C/G, CRP -757 A/G, and CRP -717 T/C gene polymorphisms; IL-6 levels; and CRP levels on the severity of periodontitis in CAD, especially in the Indonesian population." (PMID 37239434, 2023). "The additional analysis, which used variants from the vicinity of the CRP gene (cis CRP), yielded a similar effect of CRP reduction on the risk of periodontitis (OR = 0.81; 95% CI: [0.68; 0.98]; P = 0.0296)." (PMID 37342352, 2023).
periodontitis (continued). "Through data analysis, we found an association between CRP levels and periodontitis prevalence in the American population, although this association was only present in the obese population." (PMID 37481511, 2023). "Instead, CRP is a direct indicator of IL-6 signaling, and according to our analysis a possible causal mediator for the risk of periodontitis." (PMID 37342352, 2023). "A further strength of association was studied, which showed a strong association (0.531) between the severity of periodontitis and CRP." (PMID 37575815, 2023). "Studies about the relationship between IL-6 polymorphisms, CRP with chronic periodontitis, and CAD are limited, including studies on polymorphisms of IL-6-572C/G and CRP+1444 C/T." (PMID 37239434, 2023). "A meta-analysis provided robust evidence that periodontitis is linked to systemic inflammation as measured by serum CRP levels, and higher hsCRP titers were consistently associated with chronic and aggressive stages of the condition." (PMID 37873776, 2023). "IL-6 and CRP are involved in insulin resistance, and now these inflammatory factors are thought to be the cause of the adverse effect of periodontitis on glycemic control." (PMID 36904268, 2023). "This suggested that a 1-unit increase in the CRP was associated with a 20% increase in the relative risk for the development of periodontitis in the obese population." (PMID 37481511, 2023). "Previous investigations have revealed that CRP plays a vital role in the development of periodontitis, a significant cause of tooth loss, by causing the production of inflammatory mediators, such as IL-1, IL-6, and TNF-α." (PMID 38066835, 2023). "Similar studies also reported a significant association of CRP -757 T/C with chronic periodontitis in South India and high-risk TT genotypes." (PMID 37239434, 2023). "All in all, the present study evaluates the association between self-reported periodontitis and hs-CRP levels in PD patients." (PMID 35418117, 2022). "This corroborates different investigations showing that periodontitis is associated with systemic inflammation biomarkers such as CRP, IL-1 and IL-6." (PMID 35906340, 2022). "Pre-pregnancy BMI was significantly associated with increased CRP levels from pregnancy to the early postpartum period among pregnant Brazilian women with periodontitis." (PMID 35270396, 2022). "Periodontitis is also associated with increased serum levels of C-reactive protein (CRP) and decreased anti-inflammatory markers such as interleukin-10." (PMID 36009350, 2022). "To date, studies have mainly focused on the association of periodontitis with specific markers of inflammation, such as C reactive protein (CRP), fibrinogen and interleukin (IL)-6." (PMID 34385358, 2021). "The association between CRP and periodontitis received great attention in part due to the link between periodontitis and cardiovascular disease (CVD)." (PMID 34394107, 2021). "Increased levels of C-reactive protein (CRP) have been associated with periodontitis in systemically healthy subjects." (PMID 33804123, 2021). "When comparing different diagnoses, aggressive periodontitis was associated with 56% higher levels of CRP than chronic periodontitis (RoM [95% CI]: 1.56 [1.15; 2.12], p=0.0039, I2 = 84.9%)." (PMID 34394107, 2021). "Periodontitis is associated with increased serum levels of C-reactive protein (CRP) and pro-inflammatory cytokines (e.g., tumor necrosis factor-α), as well as decreased anti-inflammatory markers (e.g., interleukin-10)." (PMID 34769677, 2021). "A diagnosis of aggressive periodontitis was associated with an increase of CRP of 191% (RoM [95% CI]: 2.91 [1.91; 4.44], p<0.0001, I2 = 98.6%) and of hs-CRP of 179% (RoM [95% CI]: 2.79 [1.68; 4.65], p<0.0001, I2 = 83.6%) when compared to controls." (PMID 34394107, 2021). "Patients with severe periodontitis generally have a high level of clinical attachment loss, and the mean CRP level is higher in patients with moderate periodontitis." (PMID 34211440, 2021).
periodontitis (continued). "Chronic periodontitis was associated with an increase of CRP and hs-CRP levels of 103% and 110%, respectively (p<0.0001) (RoM [95% CI]: 2.03 [1.59; 2.60], p<0.0001, I2 = 96.3% and RoM [95% CI]: 2.10 [1.62; 2.55], p<0.0001, I2 = 97.4%, respectively)." (PMID 34394107, 2021). "This systematic review confirms a strong association between periodontitis and serum levels of CRP in otherwise systemically healthy individuals." (PMID 34394107, 2021). "Periodontitis has been associated with low-grade inflammation as assessed by C-reactive protein (CRP) levels and its treatment can decrease CRP serum levels." (PMID 34394107, 2021). "Periodontitis is the cause of a systemic inflammatory process mediated by C-reactive protein, interleukin 1b (IL-1b), interleukin 6 (IL-6), and tumor necrosis factor alpha (TNF-α), among others." (PMID 33961166, 2021). "Periodontitis is also associated with elevated levels of CRP and IL-6 with varying levels of IL-6 accompanied with disease progression." (PMID 34452136, 2021). "Excess adiposity is one of the determinants of CRP elevation and together with periodontitis jointly associated with higher CRP levels in otherwise healthy adults." (PMID 32827080, 2021). "Nevertheless, the present results support the findings in our previous cross-sectional study in a Thai population: periodontitis and Owt or Ob status independently cause changes in plasma levels of inflammatory mediators, adiponectin, and CRP." (PMID 33603787, 2021). "Chronic and aggressive periodontitis diagnoses were consistently associated with higher levels of CRP and hs-CRP (p<0.001)." (PMID 34394107, 2021). "Combined diagnosis of periodontitis was associated with an increase of 80% of CRP (RoM [95% CI]: 1.80 [1.36; 2.38], p<0.0001, I2 = 99.4%) and of 109% of hs-CRP (RoM [95% CI]: 2.09 [1.78; 2.47], p<0.0001, I2 = 99.8%) when compared to healthy controls." (PMID 34394107, 2021). "In conclusion, periodontitis is associated inflammation as assessed by raised CRP levels and this is greater in those patients with more aggressive gingival inflammation." (PMID 34394107, 2021). "Periodontitis has been most strongly associated with an increase of pro-inflammatory cytokines levels and serum C-reactive protein (CRP) levels." (PMID 33481920, 2021). "Recent research found a significant association between severe periodontitis and moderate CV risk (CRP 1–3 mg/L)." (PMID 34439905, 2021). "It has been reported that periodontitis is associated with elevated circulating inflammatory molecules, including C-reactive protein (CRP)." (PMID 32150917, 2020). "Other studies have described findings similar to our results on the association between periodontitis and serum levels of CRP." (PMID 32994872, 2020). "The purpose of this cross-sectional study was to evaluate the association between periodontitis and serum levels of C-reactive protein." (PMID 32994872, 2020). "The presence of a proinflammatory status in patients with periodontitis is associated with the increase in systemic pro-inflammatory mediators, such as C-reactive protein (CRP), and stimulation of the innate and adaptive immune responses." (PMID 32512870, 2020). "In periodontitis, the levels of proinflammatory cytokines are also elevated, but plasma CRP levels are associated with severe infection of periodontal pathogen such as Porphyromonas gingivalis." (PMID 33424972, 2020). "Many large-scale prospective studies have shown that periodontitis is associated with elevated inflammatory markers in otherwise healthy populations, demonstrating that the C-reactive protein (CRP) is strongly correlated with PD severity." (PMID 32431669, 2020). "The author affirms that LGI caused by periodontitis is detectable through a very low increase of CRP levels which, if chronically maintained over time, can cause severe cumulative damage." (PMID 32486269, 2020).
periodontitis (continued). "CRP concentration tends to be higher in elderly, smoking, and diabetic patients, and chronic periodontitis was also associated with an increase in CRP levels when these variables are controlled." (PMID 33424972, 2020). "More specifically, the authors found lower levels of CD34+ and KDR+ in patients with moderate to severe periodontitis and an inverse association with high CRP levels and EPCs, supporting the evidence of a two-way relationship between periodontitis and CVD." (PMID 31817862, 2019). "Moderate to severe periodontitis has been associated to higher levels of c-reactive protein (CRP) and prostaglandin E2 (PGE2), which are important risk factors for adverse results in the pregnancy." (PMID 31835830, 2019). "Periodontitis is associated with systemic inflammation evidenced by high C-reactive protein/high asymmetric dimethylarginine levels, as well as circulating cytokines and adipokines." (PMID 31504461, 2019). "Previous studies have demonstrated an indirect association between high serum vitamin C and a direct association between high CRP levels and consequent endothelial damage in patients with periodontitis." (PMID 31817129, 2019). "The increase in systemic markers of inflammation such as C-reactive protein, interleukin 6, and tumor necrosis factor-α in the plasma of periodontitis patients supports this association." (PMID 31195790, 2019). "Periodontal treatment can also successfully reduce circulating levels of TNF-α, CRP in patients with DM associated with periodontitis; however, research about the impact of successful long-term periodontal treatment does not exist and should be done." (PMID 30356347, 2018). "This supports the notion that periodontitis is associated with an increased CRP level that has been correlated with an increased risk of CVD." (PMID 28326084, 2017). "Although an almost significant marginal association between CRP and periodontitis was observed in the present study, our findings suggest the systemic effect of local infection including periodontitis in the association between CRP and MS." (PMID 26871443, 2016). "High CRP levels in saliva during diffuse periodontitis are a marker of local process risk for the formation or progression of cardiovascular disease with risk coefficient OR 5.6." (PMID 27143814, 2016). "The main finding of this study is that not only periodontitis, BMI and female gender are related with elevated CRP: also the AA-genotype of ANRIL (rs1333048) is associated with significantly elevated hsCRP plasma levels in patients with periodontitis." (PMID 26348353, 2015). "The low-grade inflammation associated with chronic periodontitis is characterized by increased levels of circulating pro-inflammatory cytokines (IL-1, IL-6, tumor necrosis factor α) and C-reactive protein." (PMID 23526947, 2013). "The results indicate that there is a significant association between periodontitis and salivary CRP concentrations." (PMID 24551806, 2013). "It is concluded that there was an association between advanced periodontitis and elevated blood hs-CRP levels in patients with type 1 diabetes." (PMID 22322513, 2012). "Recent studies have shown an association between high levels of CRP and IL-6 and periodontitis, an association that decreases after periodontal treatment." (PMID 23009606, 2012). "Periodontitis has also been associated with elevations in circulating levels of IL-6 and C-reactive protein (CRP)." (PMID 23009606, 2012). "This study evaluated association of chronic periodontitis and periodontopathogens with CRP in systemically healthy Serbian adults." (PMID 23019501, 2011). "The data confirm that both a high extent of attachment loss, representing a widespread periodontitis, and P gingivalis counts are independently associated with elevated CRP levels." (PMID 23019501, 2011).
periodontitis (continued). "Although observational studies suggest an association between periodontitis and CRP as a risk factor in cardiovascular disease, the reason for this relationship is not fully understood." (PMID 23019501, 2011). "Periodontitis is also associated with elevated C-reactive protein levels, a phenotype for which common genetic risk factors for periodontitis and atherosclerosis have been discussed." (PMID 19214202, 2009). "Due to the potential association between periodontitis and cardiovascular disease, CRP and IL-6 have been identified as risk factors for cardiovascular disease." (PMID 20407653, 2009). "Periodontitis, the leading cause of tooth loss, has been linked to elevated serum CRP levels." (PMID 40342577, 2025). "This study aimed to evaluate the association between periodontitis stage and grade with systemic levels of C-reactive protein (CRP), interleukin-1β (IL-1β), interleukin-6 (IL-6), and tumor necrosis factor-alpha (TNF-α) and assess changes following standardized non-surgical periodontal therapy." (PMID 41440349, 2025). "Apart from the severe inflammation in periodontal tissues, periodontitis may cause a systemic inflammation reflected by increased CRP and immunoglobulin concentrations in the blood circulation." (PMID 41010819, 2025). "In addition, elevated levels of inflammatory biomarkers such as IL-6 and CRP in mothers with periodontitis are linked to impaired placental function." (PMID 40703374, 2025). "Previous studies have shown that pro-inflammatory dietary patterns—such as those high in refined carbohydrates—are significantly associated with elevated serum CRP levels, which in turn contribute to periodontal attachment loss and increased risk of periodontitis." (PMID 40880748, 2025). "Biomarkers such as CRP and eGFR could demonstrate potential predictive value in the early identification of periodontitis, facilitating timely interventions to prevent tooth loss and limit the progression of associated systemic conditions." (PMID 39859455, 2025). "Also, treatment of periodontitis and apical periodontitis are associated with improvements in circulating levels of C-reactive protein." (PMID 40521025, 2025). "Some variables were included as both predictors and as outcomes, for example, C-reactive protein (CRP) was investigated as being associated with periodontitis (PMID 37481511), but in another study, a health behavior index was investigated as a predictor of elevated CRP levels (PMID 38628050)." (PMID 40338847, 2025). "The CRP level was associated with the severity of periodontitis." (PMID 39453923, 2024). "In addition to revealing an association between periodontitis and mortality, the present study confirmed the synergistic effect of periodontitis status and CRP levels on mortality." (PMID 39453923, 2024). "Periodontitis is associated with elevated C-reactive protein (CRP) levels." (PMID 39453923, 2024). "Although the coexistence of periodontitis and elevated CRP levels may heighten the risk of mortality, previous studies have not confirmed their synergistic effect." (PMID 39453923, 2024). "Chronic and aggressive forms of periodontitis were associated with higher CRP levels in serum and in saliva than in healthy subjects, with the value for aggressive periodontitis being more than 50% higher than that for chronic periodontitis." (PMID 39797107, 2024). "Additionally, it was discovered that the prevalence of periodontitis in the American population increases with increasing CRP levels, but this association only exists in individuals with a BMI greater than 30 kg/m2." (PMID 38263194, 2024). "Previous research data has demonstrated that periodontitis has been linked with increased systemic levels of cytokines, such as interleukin-1α,1β, interleukin-6 (IL-6), C-reactive protein (CRP), TNF tumor necrosis factor-α and interferon-γ in serum or plasma of periodontal compromised individuals." (PMID 39413077, 2024).